IL1B (interleukin 1 beta)
Diseases named in the same sentence as IL1B in open-access papers (continued):
Sharing a sentence is not in itself a finding about the gene and the disease.
ischemic stroke (continued). "For all these reasons, we propose such a hypothesis that IL-1β is associated with recurrence after the first epileptic seizure in ischemic stroke patients." (PMID 32782321, 2020). "In this study, we analyzed the association between IL-1β level and recurrence after the first epileptic seizure in ischemic stroke patients using Kaplan–Meier analysis and Cox regression model, and evaluated the value of IL-1β level in predicting seizure recurrence with ROC curves." (PMID 32782321, 2020). "Pro-inflammatory cytokines including IL-1β and IL-6 are elevated in the ischemic stroke brain, which may cause morphological and functional changes in the constituent cell types of the brain." (PMID 30705764, 2019). "Furthermore, another study reported that higher levels of IL-1β and lower levels of its antagonist IL-1ra and anti-inflammatory cytokine IL-9 in the acute phase of ischemic stroke were associated with PSF in 6 and 12 months." (PMID 26166952, 2015). "Recently, it has been reported that the AIM2 inflammasome-derived IL-1β production activated triggers the expression of FasL in the spleen monocytes which evokes the apoptosis of Fas-dependent extrinsic T cells, causing an increased risk of infection by bacteria after ischemic stroke." (PMID 35173738, 2022). "Our data shows that ISO pretreatment can downregulate NLRP3, caspase-1, and IL-1β mRNA and protein levels in the retina after ischemic stroke, suggesting that the protective mechanisms underlying ISO pretreatment may be related to the direct inhibition of retinal NLRP3 inflammasome activation." (PMID 34305534, 2021). "Furthermore, polymorphisms in the human IL1A gene, as opposed to the IL1B gene, result in higher incidence of vascular malformation, and/or higher risk of ischemic stroke, further suggesting that IL-1α may exert different actions than IL-1β in ischemic stroke." (PMID 31727174, 2019). "The NLRP3 inflammasome is a multiprotein complex that becomes activated following ischemic stroke, promoting the maturation and release of IL-1β and IL-18, thereby exacerbating neuroinflammation." (PMID 41451205, 2025). "Casp3, a key executor of apoptosis, has been shown to mediate cell death in ischemic stroke, while Il1b and Tlr4 are pivotal in initiating and propagating inflammatory responses." (PMID 40002863, 2025). "As expected, TXNIP knockdown reduced the levels of NLRP3, ASC, pro-caspase-1, and IL-1β proteins, indicating that TXNIP’s role in ischemic stroke is associated with the NLRP3 inflammasome pathway." (PMID 39690856, 2025). "IL-1β is one of the most pivotal pro-inflammatory cytokines involved in the acute phase of ischemic stroke." (PMID 40869247, 2025). "In experimental animal models of ischemic stroke, IL-1β rapidly rises in blood and brain, amplifying damage." (PMID 40809171, 2025). "Inflammation plays a central role in the pathophysiology of ischemic stroke, with IL-1β recognized as a critical mediator." (PMID 41009650, 2025). "MCC950, a potent inhibitor of the NLRP3 inflammasome, significantly reduces levels of IL-1β and IL-18 in brain tissue and attenuates neutrophil infiltration in mouse models of ischemic stroke." (PMID 41451205, 2025). "In ischemic stroke-induced neuroinflammation, IL-1β, IL-6 and TNF-α are three pro-inflammatory cytokines." (PMID 40004043, 2025). "A high level of monocyte HK2 following ischemic stroke has been shown to contribute to systemic inflammation and atheroprogression through IL-1β." (PMID 40354372, 2025). "ELISA results revealed significant increases in the pro-inflammatory cytokines TNF-α, IL-1β, and IL-6 in brain tissue after ischemic stroke." (PMID 40400029, 2025). "IL-1β is a key mediator of the inflammatory response following ischemic stroke, primarily produced by activated microglia and infiltrating neutrophils via the NLRP3 inflammasome." (PMID 41451205, 2025).
ischemic stroke (continued). "Twelve genes have been reported as potential regulators of HT in ischemic stroke in previous studies: Casp3, Csf2, Ctnnb1, Cxcl12, Hif1a, Il1b, Mtor, Ptgs2, Ptprc, Tlr2, Tlr4, and Vcam1." (PMID 40002863, 2025). "This resulted in reduced infarct size and neuroinflammation (iNOS/Arg1, TNF-α, and IL-1β levels) after ischemic stroke." (PMID 40867911, 2025). "After the ischemic stroke, the microglia secrete IL-1β which can promote astrocytic changes and functions." (PMID 41035004, 2025). "THSWD also inhibited the levels of tumor necrosis factor-α (TNF-α)(P < 0.01) and interleukin − 1β (IL-1β)(P < 0.01) in brain tissue, and increased alpha and beta diversity in ischemic stroke mice, along with a certain reversal effect on different microflora." (PMID 38500092, 2024). "The NLRP3 inflammasome mainly influences the intracellular maturation of the precursors of IL‐1β/18, and its secretion into the extracellular environment triggers neuroinflammation after ischemic stroke." (PMID 38421089, 2024). "Microglial activation exacerbates cerebral tissue damage in ischemic stroke by leading to the release of pro-inflammatory cytokines such as interleukin-1 beta (IL-1β), IL-6, and tumor necrosis factor-alpha (TNF-α)." (PMID 39057078, 2024). "Microglial NKCC1 KO mice show enhanced NLRP3 inflammasome activation and interleukin-1β (IL-1β) production after an ischemic stroke." (PMID 39649720, 2024). "For example, NLRP3, CASP 1, and IL-1β were found to colocalize in cortical neurons in ischemic stroke animal models." (PMID 38920626, 2024). "Severe neuropathologies resulting from the overexpression of IL-1β have been demonstrated in an ischemic stroke model." (PMID 39766497, 2024). "Ischaemic stroke triggers the transformation of microglia into the M1 phenotype, after which they secrete IL-1β and exert neurotoxic effects." (PMID 39198723, 2024). "ATP is an important substance for signal communication between microglia and astrocytes, and ATP externalization is a key step in activating the NLRP3 inflammasome to produce inflammatory cytokine IL-1β after ischemic stroke." (PMID 37196132, 2024). "In an ischemic stroke, pro-inflammatory cytokines, containing IL-1β, IL-6, and TNF-α, are released from glial cells and/or neurons and trigger the inflammation." (PMID 38421829, 2024). "Our study revealed that ischemic stroke contributed to the upregulated pro-inflammatory IL-1β level but decreased anti-inflammatory TFG-β content, which was consistent with previous studies." (PMID 38397792, 2024). "This contributes to a reduction in infarct volume and neuroinflammation (iNOS/Arg1, TNF-α, and IL-1β levels) after ischaemic stroke, and Nrf1 acetylation plays a crucial role in this process." (PMID 39198723, 2024). "Microglia are polarized to M1 subtype within a short period of time after ischemic stroke, thereby secreting various pro-inflammatory factors, including IL-1β, IL-6, IL-18 and TNF-α." (PMID 38421829, 2024). "A middle cerebral artery occlusion model in rats revealed that MIAT knockdown suppresses neuronal apoptosis and improves neurological functions, suggesting that MIAT impairs neurological functions in ischemic stroke by regulating miR-874-3p and IL1B." (PMID 39021183, 2024). "The delivery of anti-GPVI antibody, JAQ1, was shown to mitigate inflammatory response, possibly by reducing IL-1β and polyphosphates and decreasing inflammatory cell recruitment after ischemic stroke." (PMID 39256999, 2024). "This serves as a determinant for the onset of inflammation in ischemic stroke, subsequently upregulating target genes, including IL-1β and TNF-α." (PMID 39062789, 2024). "We aimed to investigate the association between serum levels of selected cytokines (IL-1β, IFN-γ, IL-4), and vitamin D in ischemic stroke progression, and their accuracy in predicting AIS prognosis, among Sri Lankans." (PMID 38870172, 2024).
ischemic stroke (continued). "The NIHSS score, infarct volume and the levels of NLRP1, IL-6, TNF-α, and IL-1β of ischemic stroke patients in the mRS score ≥ 3 group were remarkably elevated than the ischemic stroke patients in the mRS score ≤ 2 group." (PMID 37000063, 2023). "Several substances have been found in the cerebrospinal fluid (CSF) of stroke patients, and studies suggest that TNF-α and IL-1β initiate neuroinflammation in ischemic stroke." (PMID 37840921, 2023). "On the other hand, in ischemic stroke models, AhR exacerbates infarct formation, and downregulated IL-1β and IL-6 expression was detected in AhR KO mice." (PMID 36797786, 2023). "The NIHSS score, infarct volume and the levels of NLRP1, IL-6, TNF-α, and IL-1β of ischemic stroke patients in the mRS score ≥ 3 group were remarkably elevated than the ischemic stroke patients in the mRS score ≤ 2 group (P < .05)." (PMID 37000063, 2023). "It has also been observed to reduce pyroptotic proteins such as cleaved-caspase-1, GSDMS-N, and IL-1β following ischemic stroke." (PMID 37915409, 2023). "Following an ischemic stroke, M1-like microglia release proinflammatory cytokines such as IL-1β, IL-6, and TNF-α, as well as nitric oxide synthase, activating nuclear NF-κB and causing subsequent brain injury." (PMID 36793730, 2023). "The NIHSS score, the mRS score after 90 days and the levels of NLRP1, CRP, TNF-α IL-6 and IL-1β of ischemic stroke patients in the ASITN/SIR grade 0 to 2 group were remarkably elevated than the ischemic stroke patients in ASITN/SIR grade 3 to 4 group." (PMID 37000063, 2023). "A total of 81 DEGs were in the molecular network of STAT1 targets, including genes encoding the proinflammatory cytokines IL-1β, tumor necrosis factor alpha (TNF-α), and IL-12, all of which were upregulated in microglia after ischemic stroke." (PMID 37516843, 2023). "Immediately after ischemic stroke, immune cells in the central nervous system are excessively activated, leading to the release of several inflammatory factors, such as IL‐1β, IL‐6, and TNF‐α." (PMID 37062886, 2023). "Combined vitamin A and D significantly increased vitamin A and D serum levels, decreased IL-1β serum levels, and ultimately improved clinical outcomes in ischemic stroke patients." (PMID 38024000, 2023). "Administration of a combination of vitamin A and D supplementation can significantly increase vitamin A and D serum levels, decrease IL-1β serum levels, and ultimately improve clinical outcome in ischemic stroke patients." (PMID 37760793, 2023). "MSC-exos intravenously injected into mice with ischemic stroke were shown to migrate into the brain, suppress IL-1β expression and improve angiogenesis and neurogenesis, exerting a therapeutic effect on ischemic stroke." (PMID 35761337, 2022). "After ischemic stroke, increased secretion of IL-1β activates phospholipase A2 to degrade arachidonic acid and destroy the phospholipid bilayer." (PMID 35173738, 2022). "In our study, the levels of inflammatory factors including NLRP3, Caspase-1, and IL-1β were elevated in the MCAO group, demonstrating that the NLRP3 inflammasome was associated with the development of ischemic stroke." (PMID 36262547, 2022). "Other studies have also shown that patients who develop secondary infections after ischemic stroke show higher IL‐1β and IL‐6 blood concentrations on hospital admission and along the first 3 days after hospitalization, respectively." (PMID 35971650, 2022). "As one of the most powerful pro-inflammatory cytokines, IL-1β exerts an essential role in ischemic stroke mainly through the following mechanisms." (PMID 35173738, 2022). "We previously reported that H19 increases the immune response by increasing plasma TNF‐α and IL‐1β levels after ischemic stroke; moreover, it affects the subsequent pathological outcome." (PMID 35322553, 2022).
ischemic stroke (continued). "Since the inflammatory response is involved in the pathological process of ischemic stroke, we used ELISA to observe the alteration of IL-1β and IL-18 after ischemic stroke and if exercise preconditioning can modulate their excretion." (PMID 36262547, 2022). "IL-1β exerts an essential role in ischemic stroke by aggravating the BBB dysfunction and inflammatory response, as well as activating the apoptosis of damaged cells." (PMID 36361836, 2022). "Nevertheless, polyphenols exhibited anti-inflammatory properties in obese mice after ischemic stroke, by reducing the elevation of pro-inflammatory markers in the brain including IL-1β, IL-6, MCP-1 and TNF-α." (PMID 35624723, 2022). "Activated microglia produce a plethora of neurotoxic mediators such as NO, TNF-α, and IL-1β which have direct effects on neurologic outcomes of ischemic stroke." (PMID 33757565, 2021). "Clinical studies showed that ischemic stroke led to increased levels of IL-1β, IL-6, and TGF-β in cerebrospinal fluid, blood, and brain tissue of patients." (PMID 34408211, 2021). "TNF-α acts in synergism with IL-1β to enhance neuroinflammation and brain damage after ischemic stroke." (PMID 34572077, 2021). "In experimental models of ischemic stroke, HPA system activity is associated with neuroinflammation, mediated by increased expression of pro-inflammatory cytokines TNFα, IL1β, and IL6." (PMID 34948340, 2021). "Along with TNF-α and IL-1β, IL-6 is also upregulated during the acute inflammatory phase after ischemic stroke and accumulating evidence suggests that elevated IL-6 during acute ischemic stroke is associated with poor functional outcomes." (PMID 34572077, 2021). "Inhibition of P-JNK activity rescued microgliosis and suppressed neuroinflammation by reducing the expression levels of TNF-α and IL-1β in ischemic stroke." (PMID 34206065, 2021). "After an ischemic stroke, IL-1β levels acutely increase mainly due to the activation of local microglia and invading macrophages." (PMID 33770265, 2021). "Therefore, IL-1β was an independent risk factor for recurrence of epileptic seizure, i.e., the elevated IL-1β expression level could increase the risk of recurrence after the first epileptic seizure in ischemic stroke patients." (PMID 32782321, 2020). "The canonical pathway of pyroptosis is mediated by inflammasome activation following ischemic stroke, which also processes the precursors of IL-1β/18 into their mature forms and triggers neuroinflammation." (PMID 33153475, 2020). "In conclusion, the present study determines the cellular sources of IL-1α, IL-1β, and IL-1Ra in human post-mortem ischemic stroke tissue, and the cellular sources of TNF, TNFR1, and TNFR2 in parallel tissue sections." (PMID 32503645, 2020). "It has been shown that after an ischemic stroke, the blood-brain barrier integrity was influenced by microglia via an up-regulation of pro-inflammatory cytokines including IL-1b, TNF-a, and IL-6." (PMID 32501292, 2020). "Following ischemic stroke, the microglia will be switched to the type able to stimulate inflammation, called M1, which expresses IL-1β, which is a proinflammatory cytokine with a neurotoxic effect." (PMID 32899616, 2020). "Activation of the NLRP3 inflammasome can upregulate the expression of interleukin‐1β (IL‐1β) and then promotes the central nervous system cascade inflammatory response leading to the aggravation of nerve injury in ischemic stroke patients." (PMID 32529750, 2020). "Various blood-based biomarkers were found to be significantly associated with ischemic stroke from cardioembolic etiology including BNP/NT-proBNP, d-dimer, CRP, TNF-α, IL-6, and IL-1β." (PMID 33050269, 2020). "A previous study also indicated that H19 promoted neuroinflammation by M1 microglial polarization, which lead to increased production of TNF-α and IL-1β in ischemic stroke." (PMID 33613191, 2020).
ischemic stroke (continued). "In ischemic stroke, they participate in the regulation of proinflammatory cytokines such as IL-1β and TNF-α by activating the MAPK cascade." (PMID 32714405, 2020). "ROS accumulation was able to activate the NLRP3 inflammasome, and the activated NLRP3 inflammasome subsequently mediated neuroinflammation during ischaemic stroke by secretion IL‐1β." (PMID 32990414, 2020). "In rats with ischemic stroke, therapeutic hypothermia decreases the secretion of the pro-inflammatory cytokine IL-1β, inhibits inflammatory responses, and prevents neuronal apoptosis, thereby providing favorable therapeutic outcomes." (PMID 31644666, 2019). "Our study attempts to explain the role of the genetic variants of IL1B (C(-31)T)and IL1RN, considered to be key factors regulating inflammatory processes in the development of ischemic stroke." (PMID 31480765, 2019). "Both the serum IL-1β content and IL-1β level in the brain tissue assessed by ELISA were significantly higher in ischemic stroke rats than in rats in the sham surgery group (p<0.01)." (PMID 31644666, 2019). "Hypothermia treatment significantly reduced the increase in IL-1β (p<0.05 compared to ischemic stroke)." (PMID 31644666, 2019). "IL-1β and IL-6 increased at 1 day and 3 days after ischemic stroke in both groups, with a peak at 1 day after ischemic stroke." (PMID 30705764, 2019). "Previous preclinical work in ischaemic stroke has found that the BTK inhibitor ibrutinib inhibits IL-1β maturation and NLRP3 inflammasome activation in infiltrating macrophages and neutrophils in the infarct area of the MCAO model." (PMID 30758770, 2019). "Therapeutic hypothermia suppresses the abnormal activation of CDK5 in neurons following ischemic stroke, which results in a reduction in NF-κB activity and inhibition of caspase 1, ultimately decreasing the caspase 1-dependent production of IL-1β." (PMID 31644666, 2019). "The pro-inflammatory cytokines IL-1β and TNF-α have been implicated as key contributors to ischemic stroke and reperfusion." (PMID 28769792, 2017). "Inflammatory cytokines such as TNF-α, IL-1β, and IL-6 play pivotal roles in the pathogenesis of ischemic stroke." (PMID 29234386, 2017). "Of note, in humans IL-1β levels increase in both the cerebrospinal fluid and blood after an ischemic stroke." (PMID 26473731, 2015). "The objective of this study was to investigate IL-1β secretion under disease relevant conditions, with particular reference to ischemic stroke, for which lactic acidosis is relevant." (PMID 24022484, 2013). "Contrary to our findings, Hughes and colleagues (2006) reported that IL-6 and IL-1β were significantly reduced in the brains of Ccl2-/- mice after induction of ischaemic stroke." (PMID 20942978, 2010). "IL-1β exerts neurotoxic effects in ischemic stroke and blocking its action has been shown to reduce ischemic brain damage." (PMID 18947400, 2008). "Itgam, as one of the potential core therapeutic targets in patients with ischemic stroke, may play a role by regulating the secretion of key inflammatory factors, IL-1β, IL-6 and TNF-α, and influencing neuronal apoptosis." (PMID 41181154, 2025). "However, TRPC6 activation reduces IL‐1β and IL‐6 release and NF‐κB activity in an in vitro ischemic stroke model, partly via inhibiting Ca2+ signaling." (PMID 41399206, 2025). "Despite the known anti-inflammatory roles of protectin DX and 17 HDHA, and the pro-inflammatory role of leukotriene B4, their activity in the early subacute phase of ischemic stroke appears to be influenced by complex interplays, possibly mediated by IL-1β and IL-1Ra." (PMID 41009650, 2025). "Furthermore, after ischemic stroke, activated microglia release IL-1β, which can induce astrocytes to produce NO, thereby mediating neuro-degeneration." (PMID 41035004, 2025). "In 73 ischemic stroke patients, mean IL-1β was 1.31 ± 1.54 pg/mL and IL-1Ra 810.8 ± 691.0 pg/mL." (PMID 41009650, 2025). "In the acute phase of ischaemic stroke, IL-1β contributes to neuronal injury." (PMID 41301455, 2025).